CPEB4 (cytoplasmic polyadenylation element binding protein 4)
Description:
Sequence-specific RNA-binding protein that binds to the cytoplasmic polyadenylation element (CPE), an uridine-rich sequence element (consensus sequence 5'-UUUUUAU-3') within the mRNA 3'-UTR. RNA binding results in a clear conformational change analogous to the Venus fly trap mechanism. Regulates activation of unfolded protein response (UPR) in the process of adaptation to ER stress in liver, by maintaining translation of CPE-regulated mRNAs in conditions in which global protein synthesis is inhibited (By similarity). Required for cell cycle progression, specifically for cytokinesis and chromosomal segregation. Plays a role as an oncogene promoting tumor growth and progression by positively regulating translation of t-plasminogen activator/PLAT. Stimulates proliferation of melanocytes. In contrast to CPEB1 and CPEB3, does not play role in synaptic plasticity, learning and memory (By similarity).
Synonyms: CPE-BP4; hCPEB-4; KIAA1673
Tractability: Small molecule: a structure with a bound ligand is known. PROTAC: ubiquitination databases record sites on it; its protein half-life has been measured.
Gene: Protein-coding gene on chromosome 5 (173,888,349 to 173,961,980, forward strand). Ensembl gene ENSG00000113742.
Subcellular location: Cytoplasm; Cell projection, dendrite; Cell projection, dendritic spine; Postsynaptic density; Cell projection, axon; Cell projection, growth cone; Endoplasmic reticulum; Cytoplasm, perinuclear region
Subcellular location (Human Protein Atlas): Golgi apparatus; Nucleoplasm; Vesicles
Gene Ontology:
Molecular function: protein binding; RNA binding; mRNA 3'-UTR binding; mRNA regulatory element binding translation repressor activity; ribosome binding; translation factor activity, RNA binding; nucleic acid binding; translation regulator activity
Biological process: cellular response to amino acid stimulus; cellular response to decreased oxygen levels; cellular response to glucose starvation; ionotropic glutamate receptor signaling pathway; negative regulation of cytoplasmic translation; negative regulation of neuron apoptotic process; response to ischemia; regulation of translation; translation
Cellular component: cytoplasm; nucleus; dendrite; endoplasmic reticulum; neuron projection; postsynaptic density; synapse; axon; dendritic spine; growth cone; perinuclear region of cytoplasm; postsynapse
Genetic constraint (gnomAD): Loss-of-function variants: 9 observed, 54.73 expected, observed/expected ratio (o/e) 0.16, 90% interval 0.098 to 0.29. The upper end of that interval is the gene's LOEUF score, 0.29, which puts it in group 1 of 6, group 1 being the genes least tolerant of losing a copy. Missense variants: 541 observed, 812.01 expected, observed/expected ratio (o/e) 0.67, 90% interval 0.62 to 0.71. Synonymous variants: 269 observed, 296.49 expected, observed/expected ratio (o/e) 0.91, 90% interval 0.82 to 1.
Homologues: Orthologues: chimpanzee CPEB4 (100% identical), macaque CPEB4 (100% identical), rabbit CPEB4 (99% identical), pig CPEB4 (99% identical), rat Cpeb4 (99% identical), mouse Cpeb4 (96% identical), tropical clawed frog cpeb4 (93% identical), guinea pig CPEB4 (86% identical), dog CPEB4 (80% identical), zebrafish cpeb4a (74% identical), Drosophila melanogaster orb2 (41% identical), Caenorhabditis elegans cpb-1 (25% identical), and 1 more. Paralogues in human: CPEB2 (57% identical), CPEB3 (56% identical), CPEB1 (22% identical).
Diseases named in the same sentence as CPEB4 in open-access papers:
CPEB4 is named in the same sentence as 75 diseases in open-access papers, as found by Europe PMC text mining. Sharing a sentence is not in itself a finding about the gene and the disease. The quoted sentences say what the papers report.
glioma (16 papers, 2015 to 2023). A benign or malignant brain and spinal cord tumor that arises from glial cells (astrocytes, oligodendrocytes, ependymal cells). "Our study suggests that CPEB4 is significantly expressed in human glioma and that the upregulation of CPEB4 protein is significantly associated with advanced WHO grade." (PMID 26166131, 2015). "CPEB4 was up-regulated in glioma tissues and TMZ-resistant glioma tissues at mRNA and protein levels." (PMID 33106913, 2021). "A decrease in CPEB4 expression in a glioma cell culture led to reductions in tumor size, cell proliferation rate, and microvessel density." (PMID 33789753, 2021). "The mRNA level and protein level of CPEB4 were obviously down-regulated in glioma cells transfected with si-CPEB4, while this promoting effect was reversed in glioma cells co-transfected with si-CPEB4 and miR-373-3p." (PMID 33106913, 2021). "Elevated CPEB4 expression was shown to be an oncogene in several cancers such as pancreatic cancer, glioma and gastric cancer." (PMID 34976999, 2021). "Collectively, MSC-AS1 knockdown suppressed cell growth and the chemoresistance of glioma cells to TMZ by regulating miR-373-3p/CPEB4 axis in vitro and in vivo through activating PI3K/Akt pathway." (PMID 33106913, 2021). "In summary, our study concluded that silencing FOXD2-AS1 upregulated miR-98-5p and decreased CPEB4, thus obviously inhibiting the proliferation, migration, invasion and drug resistance of drug-resistant glioma cells and promoting their apoptosis." (PMID 31770107, 2019). "Evidence has demonstrated that CPEB4 is highly expressed in human glioma and the up-regulation of CPEB4 protein is clearly related to advanced World Health Organization (WHO) grade." (PMID 31770107, 2019). "Another interesting finding was that there was significantly higher CPEB4 expression in glioma tumor tissues than that in para normal tissues." (PMID 31770107, 2019). "The expression of CPEB4 was detected in glioma tumor tissues and the para normal tissues, and the results suggested that CPEB4 expression in glioma tumor tissues was evidently higher than that in the para normal tissues (P < 0.05)." (PMID 31770107, 2019). "Results in this study demonstrated that silencing lncRNA FOXD2-AS1 inhibited migration, invasion, proliferation and drug resistance of drug-resistant glioma cells and promoted their apoptosis via enhancing the expression of miR-98-5p or decreasing CPEB4." (PMID 31770107, 2019). "CPEB4 on the other hand is overexpressed in pancreatic ductal adenocarcinoma, high-grade gliomas, and early in the development of melanoma." (PMID 28798901, 2017). "After this study, CPEB4 expression was found upregulated in most glioma patients and inversely correlated with prognosis." (PMID 27158894, 2016). "Our results clearly demonstrated a relatively higher expression level of CPEB4 in freshly prepared high-grade glioma tissue samples B430 (WHO III) and B315 (WHO IV) than in the low-grade glioma sample B099 (WHO I)." (PMID 26166131, 2015). "This study aimed to explore the value of the determination of CPEB4 expression for elucidating the mechanism of glioma, guiding clinical diagnosis and treatment, and providing an experimental basis for further investigation." (PMID 26166131, 2015). "Kaplan–Meier plots showed that the total glioma patients with high CPEB4 expression exhibited significantly shorter OS (P < 0.01) than those with low CPEB4 expression." (PMID 26166131, 2015). "We next performed IHC to examine the dynamics of CPEB4 expression in glioma tissues of different stage based on complete follow-up data and in normal brain tissues." (PMID 26166131, 2015). "This high expression level was further increased in high-grade gliomas, and the CPEB4 expression level correlated with the WHO classification (r = 0.774, P < 0.01)." (PMID 26166131, 2015). "CPEB4 was highly expressed at the mRNA and protein levels in 4 glioma cell lines and in 4 freshly prepared glioma tissues." (PMID 26166131, 2015).
glioma (continued). "Multivariate Cox regression analyses indicated that CPEB4 expression was an independent prognostic factor of poor survival in glioma patients." (PMID 26166131, 2015). "The present study initially established that CPEB4 was expressed at a higher level in a panel of glioma cell lines and tissues than in a positive control cell line or in adjacent brain tissues." (PMID 26166131, 2015). "The expression of CPEB4 in high-grade glioma was higher than that in low-grade glioma, and highly positive CPEB4 expression in the glioma tissue was significantly associated with a more aggressive tumor phenotype." (PMID 26166131, 2015). "The positive expression rate of CPEB4 in the glioma cells was increased (203/228, 89.04%), and the positive expression rate of CPEB4 in glioblastoma cells was extremely high (64/64, 100%)." (PMID 26166131, 2015). "Our data identify the potential clinical value of CPEB4 expression assessment, which will aid in the prediction of clinical outcomes of glioma patients." (PMID 26166131, 2015). "Our results demonstrated that the mean staining intensity of CPEB4 in glioma tissue, especially high-grade glioma tissue, was significantly greater than that in normal brain tissue." (PMID 26166131, 2015). "Expression of the CPEB1 and CPEB4 genes influences the formation of gliomas in the brain." (PMID 33789753, 2021). "It has been reported that for patients with glioma, CPEB4 may be a highly sensitive prognostic indicator." (PMID 33237662, 2021). "CPEB4 is upregulated and correlated to poor prognosis in patients with glioma and gastric cancer." (PMID 34976999, 2021). "Therefore, MSC-AS1 knockdown impaired the growth of TMZ-resistant glioma cells in vivo by sponging miR-373-3p and hampering CPEB4 expression via PI3K/Akt pathway." (PMID 33106913, 2021). "Furthermore, MSC-AS1 knockdown inhibited TMZ-resistant glioma growth in vivo by regulating miR-373-3p/CPEB4 axis through PI3K/Akt pathway." (PMID 33106913, 2021). "In view of the key role of CPEB4 in glioma, we wondered whether there was a connection between CPEB4 and miR-373-3p." (PMID 33106913, 2021). "The expression of CPEB4 was first detected in glioma tissues." (PMID 33106913, 2021). "In the present study, CPEB4 was raised in TMZ-resistant glioma, and it could be targeted by miR-373-3p." (PMID 33106913, 2021). "Many reports have also revealed the role of CPEB4 in glioma, as it was up-regulated in glioma, and it could be regulated by the lncRNA FOXD2-AS1/miR-98-5p axis to participate in glioma cell proliferation, metastasis, and TMZ resistance." (PMID 33106913, 2021). "Moreover, MSC-AS1 acted as a role of carcinogenic factor in glioma by sponging miR-373-3p and upregulating CPEB4." (PMID 34054957, 2021). "Overexpression of CPEB4 promotes the migration and invasion of glioma cells." (PMID 30691465, 2019). "As earlier reported, CPEB4 is highly expressed in glioma tissues." (PMID 30691465, 2019). "Evidence has also demonstrated that CPEB4 is highly expressed in human glioma." (PMID 31770107, 2019). "In conclusion, our results strongly suggest that CPEB4 overexpression promotes glioma progression and that CPEB4 may serve as a biomarker of a more aggressive glioma phenotype." (PMID 26166131, 2015). "In addition, silencing FOXD2-AS1 could inhibit the progression of glioma and promote apoptosis of glioma cells by regulating the microRNA-98-5p/CPEB4 axis." (PMID 33589576, 2021). "However, the inhibitory effect of si-MSC-AS1-1 on CPEB4 expression was counteracted by miR-373-3p inhibitor in LN229/TR and SHG-44/TR cells, suggesting that MSC-AS1 could regulate CPEB4 expression by binding to miR-373-3p in TMZ-resistant glioma cells." (PMID 33106913, 2021). "However, whether there was a link between miR-373-3p and CPEB4 in TMZ-resistant glioma remains unclear." (PMID 33106913, 2021). "CPEB4 may serve as a highly sensitive prognostic indicator for glioma patients." (PMID 26166131, 2015).
glioma (continued). "Moreover, the overall survival of glioma patients displaying high CPEB4 protein expression (P < 0.01) was clearly lower than that of those displaying low CPEB4 expression, and the high CPEB4 expression indicated a poorer survival in high-grade glioma patients (P < 0.01)." (PMID 26166131, 2015). "However, the clinicopathological significance of CPEB4 expression to glioma and its expression levels in glioma tissues and cell lines are unknown." (PMID 26166131, 2015). "We further investigated the combined effect of miR-373-3p and CPEB4 on the proliferation, apoptosis, and TMZ resistance of TMZ-resistant glioma cells." (PMID 33106913, 2021). "Western blotting and real-time PCR analyses revealed a clearly higher level of CPEB4 expression in 3 glioblastoma cell lines (SKMG-4, U87, and T98) than in a glioma cell line (SHG44)." (PMID 26166131, 2015). "Knockdown of MSC−AS1 by regulating miR-373-3p/CPEB4 axis via PI3K/Akt pathway could inhibit cell growth and TMZ resistance in glioma." (PMID 34178658, 2021). "Therefore, we investigated the expression and clinical significance of CPEB4 in glioma tissue of different WHO grades, in normal brain tissue and in human glioma cell lines." (PMID 26166131, 2015). "Immunohistochemical analysis demonstrated that CPEB4 expression in glioma tissue was higher than that in corresponding nonneoplastic brain tissue (P < 0.01)." (PMID 26166131, 2015). "Immunohistochemistry (IHC) was performed to examine the dynamics of CPEB4 expression in glioma and nonneoplastic brain tissues, and the expression of CPEB4 in cell lines and freshly prepared tissue samples was measured using Western blotting and real-time PCR." (PMID 26166131, 2015). "More importantly, high CPEB4 expression indicated a poorer survival in high-grade glioma patients (P < 0.01) while it showed no statistical significance in low-grade glioma patients (P = 0.899)." (PMID 26166131, 2015). "Unlike with CPEB1, expression of CPEB4 is increased in gliomas." (PMID 33789753, 2021). "We could not find any CPEB4 antibody from Cell Signaling Technology, so we could not comment on the antibody specificity used in the glioma study." (PMID 27158894, 2016). "The positive expression of CPEB4 was examined in 203/228 (89.04%) of gliomas in the examined cohort (1 case of WHO II was dropped from the TMA analysis), and we confirmed no or extremely weak CPEB4 expression in 2/41 (4.88%) normal brain tissue samples." (PMID 26166131, 2015).
melanoma (10 papers, 2016 to 2024). A malignant, usually aggressive tumor composed of atypical, neoplastic melanocytes. "Of these, we focused our analysis on three targets known to be associated with melanoma, CPEB4, RPN1, and HNRNPUL1." (PMID 39771522, 2024). "Together, these results emphasize a distinct impact of CPEB4 in the regulation of key mitosis-associated oncogenic networks in melanoma." (PMID 27857118, 2016). "CPEB4 may therefore endow these melanoma-associated factors for fast tuning, polyadenylating their mRNA in the cytosol and favouring translation without the time and energy needed for new transcription, splicing and exit from the nucleus." (PMID 27857118, 2016). "Researchers from the Spanish National Cancer Research Centre have identified the CPEB4 protein as a “pioneer” in melanoma development, influencing the process of melanoma formation." (PMID 39771522, 2024). "CPEB4 protein expression was also elevated by HDAC inhibition in two melanoma cell lines, where CPEB4 was described to have a function in cancer progression." (PMID 36096941, 2022). "Previous studies have reported the dependency on CPEB4 when melanoma cells progress through G1/S cell cycle checkpoints." (PMID 34976999, 2021). "By conducting RIP-Seq, researchers have found that the binding spectrum of CPEB4 is highly lineage dependent, as there is little overlap among CPEB4-bound mRNAs between melanoma and pancreatic cancer." (PMID 32968053, 2020). "CPEB4 is highly expressed in the early stage of melanoma progression; it can control the polyadenylation of the melanoma drivers, MITF and RAB7A, through binding to their 3′-UTRs." (PMID 32967226, 2020). "Filtering for significance (adjusted P value<0.05), this approach rendered 331 CPEB4-bound transcripts in melanoma cells (that is, downregulated in the CPEB4 shRNA counterparts)." (PMID 27857118, 2016). "Here the authors identify a lineage-specific requirement of the cytoplasmic polyadenylation binding protein 4 (CPEB4) in malignant melanoma and show that it controls melanoma drivers MITF and RAB27A." (PMID 27857118, 2016). "CPEB4 is upregulated early in melanoma progression, as defined by computational and histological analyses." (PMID 27857118, 2016). "Melanoma cells are distinct from other tumour cell types in their dependency on CPEB4, not only to prevent mitotic aberrations, but to progress through G1/S cell cycle checkpoints." (PMID 27857118, 2016). "The minimal overlap in the CPEB4-bound transcripts in melanoma and pancreatic cancers is striking, considering that up to 20% of the transcriptome has been proposed to be controlled by cytoplasmic polyadenylation." (PMID 27857118, 2016). "The G2/M transition modulators identified as CPEB4 targets in melanoma provide a mechanistic explanation for the aberrant mitosis observed in vitro and in vivo upon depletion of this protein." (PMID 27857118, 2016). "Altogether, these results point out to distinct roles of CPEB4 in melanoma that (i) cannot be compensated for by other CPEBs and (ii) reflect intrinsic features of this disease that extend beyond the basal levels of CPEBs across tumour types." (PMID 27857118, 2016). "Here we identify a lineage-specific requirement of the cytoplasmic polyadenylation binding protein 4 (CPEB4) in malignant melanoma." (PMID 27857118, 2016). "Publicly accessible transcriptomic profiles were mined for a global evaluation of CPEB4 mRNA expression in melanoma and to identify possible differences with other malignancies." (PMID 27857118, 2016). "CPEB4 sgRNAs promoted a marked inhibition of MITF in pigmented melanoma cells with the consequent blockade of cell proliferation." (PMID 27857118, 2016). "Performing a computational analysis of CPEB proteins across tumour types, we found a high expression of CPEB4 in melanoma cells." (PMID 27857118, 2016). "Essential in these CPEB4-controlled networks are the melanoma drivers MITF and RAB7A, a feature validated in clinical biopsies." (PMID 27857118, 2016).